IL10 (interleukin 10)
Diseases named in the same sentence as IL10 in open-access papers (continued):
Sharing a sentence is not in itself a finding about the gene and the disease.
influenza (continued). "This INFγ/IL-10 ratio was significantly lower in the SCD group compared to healthy donors suggesting a cytokine imbalance after influenza vaccination." (PMID 31600331, 2019). "Low levels of INFγ/IL-10 ratio have been documented in subjects with laboratory confirmed influenza among vaccinated subjects and correlated with illness severity." (PMID 31600331, 2019). "During acute influenza infection, blocking IL-10 response resulted in increased pulmonary inflammation and increased mortality." (PMID 31803193, 2019). "We also document an imbalance of cytokines after influenza vaccination in SCD individuals with an INFγ/IL-10 ratio (Th1-type/Treg-type response) significantly lower in the SCD cohort." (PMID 31600331, 2019). "We further investigated a cytokine ratio reflecting the Th1-cytokine type response, mainly involved in the anti-influenza mechanism, relative to the Treg-cytokine type activity (INFγ/IL-10)." (PMID 31600331, 2019). "IL-10 can interfere with protective immunity following a high-dose influenza challenge by inhibiting Th1 and Th17 responses, and blockade of IL-10 protects naïve mice against an otherwise lethal influenza challenge." (PMID 31803193, 2019). "In lung homogenates, influenza by itself caused mildly elevated levels of TNF-α, IL-1β, IL-6, and IL-10 at 4 days post-infection and to a lesser extent at 10 days after infection." (PMID 29978355, 2018). "Plasma concentrations of the anti-inflammatory cytokine IL-10 were however significantly enhanced in mice challenged with LPS 4 days after influenza infection." (PMID 29978355, 2018). "LPS-induced plasma levels of the anti-inflammatory cytokine IL-10 were enhanced 4 days after influenza infection, whereas a trend towards increased pulmonary IL-10 concentrations was found." (PMID 29978355, 2018). "Intriguingly, our data also demonstrate that a small population of IL-10+IL-21+Tfh cells also develop during PR8-influenza." (PMID 30487586, 2018). "For example, knockout of IL-10 is beneficial as it allows immediate protection against acute influenza with better survival at lethal infection levels." (PMID 30619303, 2018). "Meanwhile, CD8+ T cells have previously been identified as the main producer of IL-10 in the lungs during influenza infection." (PMID 28270815, 2017). "Our data demonstrates a mechanism whereby exposure to EPFRs alter pulmonary immune responses via the induction of Tregs and IL10 and modulate the protective immune responses against influenza infection." (PMID 28086957, 2017). "To further understand the role of IL10 in mediating EPFR-induced immunosuppression and further leading to exacerbated influenza disease severity, we exposed mice deficient in IL10 (B6.129P2-Il10tm1Cgn/J; IL10−/−) to EPFRs and infected them with influenza." (PMID 28086957, 2017). "Our results showed that indirubin treatment lessened the production of TNF-α, IL-1β and IL-6 while enhanced the production of IL-10 in the lung tissues of influenza-infected mice loaded with stress." (PMID 29285277, 2017). "It was already shown that pregnant women with influenza also present with increased concentrations of IL-10." (PMID 29255607, 2017). "Neonatal mice exposed to EPFRs had a significant increase in pulmonary Tregs and the immunosuppressive cytokine IL10 following influenza infection, which coincided with decreased protective T cell responses to influenza infection at 6 dpi." (PMID 28086957, 2017). "In a previous study of influenza-infected PICU patients, all but GCSF and IL10 were previously associated with mortality." (PMID 29163498, 2017). "In mice, a population of IL-10-producing CD8+ Tregs controlling CD8+ Teff responses during influenza infection expressed higher level of GITR." (PMID 29445370, 2017). "Many CD4+ T-cells responding to influenza in the lung produce IL-10, largely in cells also producing IFN-γ." (PMID 28769922, 2017).
influenza (continued). "To address this question, we first examined the kinetics of Treg and IL10 induction during the exposure to Air/EPFRs during influenza infection (Air/Flu or DCB/Flu)." (PMID 28086957, 2017). "Studies have shown that the age-related decrease in antibody response to influenza vaccination is correlated with extrinsic factors, including impaired T-cell help, poor DC function, and high IL-10 production by monocytes/macrophages." (PMID 28769922, 2017). "Ten days after influenza infection, we observed more IL-10 and less Eotaxin in mice that consumed L. paracasei compared with control group." (PMID 28931041, 2017). "Co-administration of IL12 and influenza subunit vaccine to newborn mice led to increased splenic expression of IFNγ, IL10 and IL15 mRNA and enhanced protective efficacy of antiviral immunisation." (PMID 29124321, 2017). "Neonatal exposure to EPFRs induced Tregs and IL10 resulting in suppressed adaptive T cell responses and enhanced influenza disease severity in neonatal mice." (PMID 28086957, 2017). "This IL-10 production by influenza-specific CD4+ T-cells results in reduced protection by suppressing cytokine production in Th17 cells, but also plays an important role in limiting immunopathology." (PMID 28769922, 2017). "In influenza infections, coproduction of IL-10 and IFN-γ facilitates anti-influenza antibody accumulation in the lung mucosa." (PMID 28316998, 2017). "The dysregulation of IL-10 production from monocytes suggests its potential role in impaired influenza vaccine responses in older adults." (PMID 28769922, 2017). "Our future studies are focusing on the source of IL-10 production and how the T-cell response to influenza can be enhanced through the use of vaccine adjuvants." (PMID 26941738, 2016). "We have shown that older people who develop influenza illness have low levels of the cytolytic mediator, granzyme B (GrB), and a lower ratio of IFNγ:IL-10 released from peripheral blood mononuclear cells (PBMC) following challenge with live influenza virus." (PMID 27322555, 2016). "Previous work has also suggested a role for the anti-inflammatory cytokine, IL-10, in modulating macrophage function after influenza infection." (PMID 27701435, 2016). "We observed that while production of both IFNγ and IL-10 in whole PBMCs declined with age, the IFNγ:IL-10 ratio declined, suggesting a possible shift toward a more anti-inflammatory response to influenza." (PMID 27322555, 2016). "One candidate factor is the immunosuppressive cytokine IL-10, which is known to be produced massively in the context of influenza infection." (PMID 27803187, 2016). "Although IL-10 has been shown to improve outcomes during influenza infection, the results of co-infection studies using post-influenza bacterial models have been mixed." (PMID 25651926, 2015). "Previous studies have shown that type I interferon promotes resolution of viral load during influenza infection through IL-10 production and exogenous IL-10 improves mortality and decreases lung pathology in IFNαR null mice infected with influenza." (PMID 25651926, 2015). "Type I interferon has been shown to promote resolution of viral load during influenza through IL-10 production." (PMID 25651926, 2015). "IL-27 has also been shown to cooperate with IL-2 from CD4+ helper T cells to induce IL-10 through a Blimp-1 dependent mechanism during influenza infection." (PMID 25651926, 2015). "In the singularly influenza-infected IL-10−/− mice, there was increased neutrophilia compared to the influenza-infected WT mice (6B)." (PMID 25651926, 2015). "Multiple recent studies have suggested that IL-10 plays a critical role in the resolution of influenza infection." (PMID 25651926, 2015).
influenza (continued). "However, IL-10 has also been implicated as a mediator of enhanced lung susceptibility to numerous bacterial infections, including secondary Streptococcus pneumoniae infection following influenza, primary Klebsiella pneumoniae pneumonia, and Pseudomonas aeruginosa sepsis in murine models." (PMID 25651926, 2015). "Recently, IL-10 was shown to decrease lung pathology in a murine model of severe influenza infection." (PMID 25651926, 2015). "IL-27 receptor α knock-out mice infected with influenza displayed significantly decreased IL-10 production compared to wild-type." (PMID 25651926, 2015). "We examined levels of IL-10 production in both WT and IL-27Rα−/− mice co-infected with influenza, S. aureus." (PMID 25651926, 2015). "Exogenous IL-10 improves mortality and decreases lung pathology in both WT and IFNαR−/− mice infected with influenza." (PMID 25651926, 2015). "IL-10−/− mice showed significantly decreased S. aureus bacterial burden during co-infection, confirming that IL-10 plays a part in post-influenza secondary bacterial pneumonia." (PMID 25651926, 2015). "IL17 has been implicated as super-inducer of neutrophil infiltration and acute lung immuno-pathology following influenza infection, with counteractive dampening interactions by IL10." (PMID 24475142, 2014). "More specifically, the IL-10 production is thought to prevent this overexuberant inflammatory response to an influenza infection." (PMID 24719769, 2014). "It seems that the role of IL-10 during influenza is probably dependent on the timing of IL-10 signaling." (PMID 24893655, 2014). "This view is consistent with our findings on the level of IL-10 expression during the recovery/resolution phase of influenza infection." (PMID 25144228, 2014). "For example, Th17 cells are able to mount a protective response in primary lung infection with influenza in IL-10 KO mice suggesting that Th17 cells are particularly susceptible to IL-10 mediated suppression." (PMID 24606807, 2014). "SOCS1−/−IFN-γ−/− mice exhibited significantly decreased production of IL-6 and IL-10 at 7 dpi but increased IL-4, IL-5 and IL-13 levels in airways during influenza infection." (PMID 25500584, 2014). "As a major anti-inflammatory cytokine, IL-10 has been shown to be crucial in regulating the magnitude of inflammation during influenza infection." (PMID 25500584, 2014). "We previously reported that oral administration of the soluble components of LFK, lysozyme-treated lactic acid bacteria E. faecalis FK-23, has an anti-influenza effect by upregulation of the anti-inflammatory cytokine IL-10 in lung." (PMID 23853748, 2013). "Recent studies have shown a potential role for IL-10 inhibition in decreased immune mediated pathology and better clinical outcomes of influenza." (PMID 23478252, 2013). "While IL-1ra treatment has been shown to increase the survival rate of influenza-infected mice, the impact of IL-10 on the outcome of influenza infection in mouse models is still controversial." (PMID 21966414, 2011). "It is of interest that RSV infection induced a lower level of IL-10 release into the infected airways relative to the release of effector T cells derived pro-inflammatory effector cytokine IFN-γ than detected in influenza infected lungs." (PMID 21829368, 2011). "In contrast, we found markedly increased levels of cytokines with anti-inflammatory properties including IL-10 (p = 0.005 and 0.002) and IL-1Ra (p = 0.01 and p = 0.003) in influenza-infected patients." (PMID 21966414, 2011). "IL-10 produced by influenza-specific Th1 cells had a crucial role in suppressing excess inflammation and associated immunopathology." (PMID 19751267, 2009). "We consider the decrease in anti-inflammatory IL-10, after the administration of the influenza vaccine as a response to the reduction in pro-inflammatory cytokines, since the regulation of the inflammatory response is carried out according to the principle of negative correlation." (PMID 39937802, 2025).
influenza (continued). "Importantly, Spring PM exposure prior to influenza infection increased release of several cytokines as measured at 24 h p.i. which are indicative of cytokine storm in influenza infection: IL-6, IL-8, IL-10, and MCP-163–64." (PMID 40671793, 2025). "Since high serum levels of IL-10 can also be found in patients infected with seasonal influenza strains, this mechanism could lead to immunopathology during seasonal, pandemic, and avian infections." (PMID 40431705, 2025). "Additionally, the study focused primarily on IFN-γ and IL-10 as cytokine markers, potentially overlooking other critical inflammatory mediators involved in influenza pathogenesis." (PMID 39850538, 2025). "IL-27 induces IL-10+ secretion by IFNγ+virus-specific T cells (Tr1-like cells), controlling exacerbated inflammation and conferring host protection from immunopathology in the lung during influenza infection." (PMID 38966644, 2024). "In comparison to the Model group, the serum IL-10 levels remained essentially unchanged in the Control and the Mix groups, potentially playing a role in maintaining immune system equilibrium during the influenza infection." (PMID 39410114, 2024). "Moreover, the IL10 rs1800896 AG genotype was substantially related to death in infections with influenza A/H1N1pdm09." (PMID 36882862, 2023). "The increases in IL-10 in the lung could interfere with neutrophil accumulation and promote secondary bacterial infections such as Streptococcus pneumoniae after influenza, as well as insufficient clearance of bacteria from the lung." (PMID 38585537, 2023). "IL-10 is highly abundant in influenza infection, especially during the adaptive immune response." (PMID 38249419, 2023). "The role of effector T cell-derived IL-10 has been established in pulmonary immunomodulation during primary flu, while the role of Treg cell-derived IL-10 in host defense and immunopathology during primary and secondary influenza infections remains to be elucidated." (PMID 36159872, 2022). "Thus, the expression of IL-10 inhibits the development of Th17 responses during influenza infection, and this is correlated with impaired protection during the primary, but not secondary, high-dose challenge." (PMID 34064728, 2021). "Moreover, it has been reported that geniposide can enhance the protective mechanism of anti-inflammation and immune regulation by enhancing the expression of IL-4 and IL-10, so as to play an anti-influenza role." (PMID 34867371, 2021). "Our curation indicates that the cytokine response induced by SARS-CoV-2 is different compared to other CRS-causing respiratory viruses, as SARS-CoV-2 does not always induce specific cytokines like other coronaviruses or influenza do, such as IL-2, IL-10, IL-4, or IL-5." (PMID 33732251, 2021). "The purpose of our study conducted over four consecutive influenza seasons was to compare antibody, IFNγ, IL-10, and GrB responses to vaccination among older adults randomized to receive the seasonal formulations of HD-SVV vs. SD-SVV, and a young adult control group who received SD-SVV." (PMID 35128529, 2021). "The reduced IL-10 response in young children may partially explain why they are among the most vulnerable to developing severe influenza." (PMID 33680987, 2021). "We also conducted multiplex measurement on cytokines and chemokines at day 7 p.i. in lung tissues using Luminex 200, and similarly, we found significantly higher production of IL-1β, IL-6, TNF-α, IL-10, MCP-1, IP-10, and IFN-γ caused by influenza infection on day 7 p.i.." (PMID 35154087, 2021). "A study conducted on 246 patients infected with A/H1N1pdm09 virus in India, suggested that SNPs in the IL-10 and TNF-α genes might be associated with disease severity in influenza A/H1N1pdm09-infected patients." (PMID 33766078, 2021).
influenza (continued). "Influenza-pneumococcal coinfection in dendritic cells synergistically upregulates pro-inflammatory cytokines, whereas anti-inflammatory cytokines, like IL-10, are downregulated by influenza, which might contribute to the immunopathology during coinfection." (PMID 33828999, 2021). "In influenza infection, IL-10 is highly abundant, especially during the adaptive immune response." (PMID 32475230, 2020). "For example, TNF has immune regulatory, proinflammatory, and anti-viral functions, MAPK8 modulates lymphocyte homeostasis, IL10 is generally considered to be an anti-inflammatory cytokine, but production of IL-10 has also been shown to be detrimental during high-dose primary influenza challenge." (PMID 32754224, 2020). "Importantly, we have shown in in vitro experiments that there was an increase in the IFNγ:IL-10 ratio and GrB activity in response to influenza challenge when the TLR4 agonist GLA-SE was combined with SVV." (PMID 32399058, 2020). "On the other hand, other studies have demonstrated that ex vivo T cell parameters (e.g., interferon (IFN)-gamma and IL-10 ratio, granzyme B levels) measuring cellular immune responses to influenza challenge performed better than antibody titers as correlates of vaccine efficacy in older adults." (PMID 33178213, 2020). "Regardless, this critical observation complicates IL-10's role in influenza infection." (PMID 32974217, 2020). "The slight IL-10-induced reduction in HA/NA VLP entry also appears consistent with previous observations regarding the effects of macrophage polarization on influenza infection of these cells." (PMID 31547585, 2019). "Whether MAIT cell functions are affected by influenza, for instance through IL-10 or type I IFNs, is still ignored." (PMID 30881357, 2019). "Furthermore, neutralization of IL-10 and IL-27 by blocking antibodies during the course of influenza restores the respective abilities of NKT cells and γδ T cells to combat secondary bacterial infections." (PMID 30881357, 2019). "The fact that we found impaired Mtb-specific CD4+ T cell responses and evidence for AAMs concomitant with increased Il10 expression in coinfected mice prompted us to determine the role of IL-10 receptor (IL-10R) signaling in influenza-induced exacerbation of Mtb infection." (PMID 30998505, 2019). "Along with IL-10, type I IFNs favor bacterial superinfection post-influenza." (PMID 30881357, 2019). "Importantly, however, our data additionally indicate that the formation of IL-10+IL-21+Tfh cells during influenza appears to be rather transient." (PMID 30487586, 2018). "However, inhibiting IL-10 after acute influenza infection results in tissue inflammation and damage, with decreased survival, similar to IL-10 knockout S.pneumoniae bacterial models." (PMID 30619303, 2018). "However, in contrast to chronic LCMV infection, IL-10+IL-21+Tfh cells rapidly declined in influenza-infected hosts." (PMID 30487586, 2018). "IL-10 plays an essential role in pulmonary inflammatory diseases, which has been reported in multiple murine models of lung disease, including allergic asthma, hypersensitivity pneumonitis (HP) and influenza pneumonia." (PMID 30510554, 2018). "IL-10 is enhanced following influenza infection and promotes bacterial replication in the post-influenza virus infected lung by inhibiting multiple facets of immunity; a process that may be driven by the upregulation of indoleamine 2,3-dioxygenase (IDO)." (PMID 30619303, 2018). "Upon infection with influenza, we observed a second induction of IL10 (6 dpi in DCB/Flu lungs)." (PMID 28086957, 2017). "We also studied whether IL10 was the effector molecule responsible for EPFR-enhanced flu severity in neonatal mice." (PMID 28086957, 2017). "This discrepancy may be explained by the time when we measured IL-10 in the lungs, since the main contributors to IL-10 production in the context of influenza infection are CD8+ effector T cells, a population of cells that is found later in infection." (PMID 28351919, 2017).